CD40 (CD40 molecule)
Diseases named in the same sentence as CD40 in open-access papers (continued):
Sharing a sentence is not in itself a finding about the gene and the disease.
infection (continued). "However, on day 4 post infection, the frequencies ofthe activation markers CD40+ and CD86+ on mDCwere significantly higher in the TLR group (4.418% ±0.231%SEM) compared to all other groups (DENV/TLR: 3.66% ±0.080%SEM, p<0.021; DENV: 0.950%±0.320% SEM, p<0.001;Control: 1.233% ±0.190% SEM,p<0.001)." (PMID 21559444, 2011). "The genes for which the expression was higher in the lungs of WT than those of IFN-γR−/−mice in response to H37Rv infection included Mhc-II, CD274, Cd86, and Cd40, which are all involved in the synapse between antigen-presenting cells and T cells." (PMID 38803236, 2024). "We used a cohousing mouse model of Pneumocystis infection, combined with flow cytometry and qPCR, to examine the ability of different populations of cells from C57BL/6 mice to reconstitute immunity in CD40 knockout (KO) mice." (PMID 38410485, 2024). "To further investigate the role of glycolysis in the effector function of CD1c+ mDCs in response to infection with BCG, we analyzed the cell surface expression levels of the costimulatory molecule CD40 and the chemokine receptor CCR7." (PMID 37475964, 2023). "Loss of CD40 signaling led to greater mortality beginning on day 7 and is likely multifactorial, with enhanced mortality resulting from an absence of viral control early during infection as well as deficits in the recruitment and activation of adaptive immunity at later times." (PMID 37376652, 2023). "The dynamics and interaction between CD4+CD25+ and co-stimulatory molecules such as CD28, CD80, CD40 and CD40LG during infection with A. phagocytophilum in sheep needs further investigation in the future." (PMID 37989861, 2023). "In order to assess the activation status of these infected cells ex vivo, we first examined the expression of the activation markers CD40 and CD80 on T. cruzi-infected cells from the infection site." (PMID 36695605, 2023). "And we also investigated the expression of cell-surface markers in splenic MΦs, the results showed that the levels of CD40, CD80 and CD86 both increased significantly at 96 h following i.v infection." (PMID 38012553, 2023). "In particular, splenic cDC expressed higher levels of CD40, CD80, and CD86 from 4 h to 48 h post-infection compared with 0 h, especially at 4 h, with values of 21.1% ± 5.3 (p = 0.028), 48.1% ± 5.0 (p = 0.018), and 36.2% ± 3.1 (p = 0.009), respectively." (PMID 36977141, 2023). "Our meta-analyses indicated that five out of the eight significantly identified genes (CD40, ICOS-L, SLAMF1, CD84, IL-21R) were downregulated continuously during infection." (PMID 37146079, 2023). "We also tested the mechanism of CD40-mediated antiviral signaling and found that T-cell-Mφ interactions led to IL-12 production, which in turn promoted IFN-γ-dependent protection from infection." (PMID 37376652, 2023). "Compared to saline-Fc treated mice, Sema3E-Fc treated WT, and Sema3E KO mice showed higher MHC‐II, CD40, CD80, and CD86 molecules on the surface of DCs following infection." (PMID 35983029, 2022). "Professional hematopoietic APCs upregulate MHCII and costimulatory receptors (CD40, CD80, and CD86) under inflammatory conditions triggered by infection, injury, and/or stress." (PMID 36227687, 2022). "(G) Quantification of median fluorescence values of co-stimulatory molecules (CD40, CD80, and CD86) on WT DCs stimulated with ON (black) or ON after pre-treatment of DCs with 50 mM FK506 for 20 min prior to infection (green)." (PMID 35881547, 2022). "After infection with Mtb, osteoblast cells were treated with soluble CD154/TRAP fusion protein for the ligation of CD40." (PMID 35463641, 2022). "After poly I:C treatment and seven days of CB4 infection, APCs (CD11b+CD11c+, CD11b+CD11c-) isolated from PLNs and spleens of MDA5+/- mice express similar levels of CD40 and CD86 compared to untreated CB4-infected MDA5+/- mice." (PMID 34804036, 2021).
infection (continued). "First, DC isolated from SND1-/- mice exhibited significantly lower CD40/CD80/CD86 expression and IL-12 production, but higher IL-10 production than wild-type mice during Cm infection." (PMID 33635920, 2021). "S. Typhimurium-infected chMoDCs showed significant upregulation in the expression of costimulatory (CD40, CD80, CD83 and CD86) and MHC molecules at 6 h post-infection in comparison to S. Gallinarum." (PMID 34446765, 2021). "This study showed that RSA59 infection induces a significant upregulation of CD4+ T cell activation marker and costimulant for CD40 on microglia/macrophage, CD40L in WT mice." (PMID 34898656, 2021). "Splenic SND1-/- DCs showed lower expression of CD40, CD80 and CD86 molecules than splenic wild-type DCs especially at day 7 following infection both in frequency and mean fluorescence intensity." (PMID 33635920, 2021). "Both cell mediated and humoral responses to pathogen infection are dependent upon the co-stimulatory signal resulting from T cell CD40 ligand (CD40L, CD154) ligation with CD40 on antigen presenting cells." (PMID 35111692, 2021). "Receptors and ligands of the TNF superfamily are also expressed transcriptionally following infection in BMDMs including CD70, CD40, OX40L and 41BBL, of which surface expression of OX40L appears most sensitive to induction by T. gondii infection." (PMID 32853276, 2020). "The increased expression of CD40, CD54, CD80, CD86, and MHCII in DC2.4 dendritic cell line has been reported after infection with M. smegmatis and M. bovis BCG expressing an epitope from ovalbumin." (PMID 33260418, 2020). "Mean fluorescence intensity signifying the estimate of surface expression of CD80, CD86, CD40, MHC I, and MHC II on macrophages increased significantly upon infection with Ms_Rv1954A as compared to Ms_Vc." (PMID 33163415, 2020). "Infection of BMDM with live PS-sensitized (black bar) and WT Lb (dark gray bar) elevated the MFI of both CD40 and CD86 molecules above the ground levels of BMDM alone (light gray) and those light-exposed (blank)." (PMID 33051524, 2020). "However, it remains unclear how CD40 expression is regulated in DCs during LD infection." (PMID 33370418, 2020). "The expression of MHC II, CD40, and CD86 in Fo B cells and plasmablasts was significantly decreased in TNF-/- mice at week 3 after infection." (PMID 32742607, 2020). "In contrast, both CD40 and MHC class II showed greater up-regulation during infection of moDCs from donors with higher viral replication." (PMID 28152048, 2017). "As expected, LPS treatment augmented CD40-postive and CD86-positive CD11c+ DCs as compared to the mock infection." (PMID 28150813, 2017). "We also investigated the effects of CD40 on endogenous STING expression in different cell lines and in mice after infection with N67 parasite." (PMID 27716849, 2016). "Expression of MHC class II (p < 0.001), CD40 (p = 0.032) and CD80 (p = 0.044) were significantly enhanced following infection of DCs with BCG compared with uninfected DCs." (PMID 27530534, 2016). "After infection with the H9N2 virus for 24 h, the CD86, CD80, and CD40 expression levels in the DCs were significantly increased compared to the untreated group." (PMID 27826541, 2016). "Further studies to look at B-cells activating marker CD40 expressed on infected PBMCs showed that EBV-wt, EBVΔE3C, EBVΔ183–240 and EBVΔ621–675 had similar levels of CD40 activation at 24 hrs post-infection." (PMID 26336822, 2015). "To test the maturation status of NSR infected DCs, we analysed surface expression of MHC-I, MHC-II, CD40, CD80, CD83 and CD86 molecules upon infection." (PMID 26575844, 2015). "L. major amastigotes can modulate the signaling pathway downstream of membrane CD40 engagement by inducing ERK1/2 and IL-10 production, which inhibits the p38MAPK/IL12 pathway resulting in replication of parasite and persistence of infection." (PMID 26488744, 2015).
infection (continued). "By 14 days post-infection, expression of MHC II was higher on CD11c+ DC, as well as a greater percentage of DC were CD40+." (PMID 23390557, 2013). "Surface expression of MHC II, CD40, CD80, and CD86 were significantly (p<0.05) up-regulated at 20 h after infection with O. tsutsugamushi, even though the levels of expression were lower than those of cells stimulated with LPS." (PMID 23301113, 2013). "Here we explore the incorporation of two CD40 mimics, Epstein Barr Virus gene LMP1 or an LMP1-CD40 chimera, into a strain of SIV that was engineered to be limited to a single cycle of infection." (PMID 21592361, 2011). "Recently it has been demonstrated that HIV-1 promotes CD4+ T cell infection by inserting CD40L into emerging viral particles and trans-activating B cells in a CD40 dependent manner." (PMID 20967291, 2010). "MHCII and costimulatory molecules CD40, CD80, and CD86 had an average 0.5 fold decrease in their MFI intensity from three to ten weeks after infection." (PMID 20625513, 2010). "In comparison with the CD8− DC isolated from BCG infected mice iCD8− DC, the CD8+ DC isolated from the mice with the same infection iCD8+ DC expressed higher CD80 (65.66% vs 17.43%), CD86 (57.43% vs 30%) and CD40 (44% vs 35%) molecules." (PMID 20174628, 2010). "We used a panel of surface antigen markers CD5, CD10, CD19, CD23, CD39, CD40 & CD44 and the intracellular marker Ki-67 to correlate B-cell activation with proliferation during the early stages of infection up to 7 days." (PMID 19784370, 2009). "Here, we demonstrate that H1N1-infected pulmonary microvascular ECs (PMVECs) during later stage of infection function as antigen-presenting cells that activate resident CD8+ T cells via MHC-1 and co-stimulatory CD40, promoting viral clearance through IFNγ-STAT1-dependent positive feedback loop." (PMID 41542053, 2026). "Namely, CD5, CD8A, CD6 and CD244, C-C and C-X-C motif chemokines (CXCL5 CXCL6, MCP-4, and CCL20), as well as CD40, PDL-1, CUB domain-containing protein 1 (CDCP1) and interleukin-12B (IL-12B) were elevated in the late infection group compared to the unexposed group." (PMID 41510260, 2025). "The absence of CD40 signaling weakens macrophage polarization towards the pro-inflammatory state and even promotes host mortality under low-dose infection condition." (PMID 40746551, 2025). "In addition, CD40‐positive PEA2, also displayed a significantly lower viability post LOAd703 infection compared to LOAd(−) infection." (PMID 38494863, 2024). "Similar to WT STm infection, genes involved in the regulation of immune responses (ATF3, BATF3, ETS2, IRF9, NFκB2, MAFA, TNFAIP3), effector functions, (CCL4, CD200L, CD40, CD72, CD80, IL18) and TLR signaling, (EAF2, TLR15, TRAF3IP2, TOLLIP) were upregulated after ΔprgH STm infection in both models." (PMID 37854334, 2023). "We observed no reduction in MHC-II, CD80/86 and CD40 expression after infection, and similar levels of IFNγ production by Th1 cells were observed in time course studies." (PMID 38114497, 2023). "Collectively these data establish that interruption of CD40:CD40L interactions enhances resistance to Brucella, and suggest disrupting GC B, TReg, TFH, and/or TFR populations may improve control of infection." (PMID 37721965, 2023). "Along with CD38, CD274 (PD-L1) and CD40 also presented a higher expression in the IND group after infection although no significance was observed." (PMID 35873155, 2022). "Notably, we found that the expression of specific markers of M1 type microglia (Aif1, Cd86, Cd40, Ccl2, Ccr2, Cx3cr1, IL-1β, IL-6, and NOS2) was elevated post infection." (PMID 36618398, 2022). "Furthermore, our results demonstrate that despite an upregulation of CD40, CD169+ M2 macrophages downregulate CD86 and MHC-II expression upon infection with SARS-CoV-2." (PMID 34122407, 2021).
infection (continued). "Before infection, FSClow DCs of uninfected chickens showed a higher expression of MHC-II and more cells that were positive for the costimulatory molecules CD40 and CD80 compared to FSChigh DCs." (PMID 34404469, 2021). "It was evident the enhanced expression of MHC-II and CD40 molecules in rMs064 infected macrophages 24 h post-infection, compared to non-infected and rMs012 infected macrophages." (PMID 33260418, 2020). "As we expected, the expression and MFI of plasma cell-expressing CD40 and CD86 in BTNF-/- and TNF-/- mice were comparable to those of TNFf/f mice at week 3 after infection." (PMID 32742607, 2020). "Expansion and maintenance of memory CD8+ T cells are CD4+ T‐cell‐dependent in numerous infection models, with data supporting an essential role of CD4+ T cells in aspects of initial memory CD8+ T‐cell priming through factors such as CD27 and CD40 signalling." (PMID 33005416, 2020). "Infection with the S. aureus USA300 WT or the S. aureus Δαβδ mutant strain induced the up-regulation of MHCII, CD86, CCR7, CD80, CD40, and PD-L2 on all DC subsets in the spleen starting 6 h pi compared to PBS-treated mice as analyzed by flow cytometry staining." (PMID 31134074, 2019). "In order to assess the role of CD4+ T cells in providing a CD40 stimulating microenvironment as well as in exerting immune control in vivo, we depleted these cells with a CD4 specific antibody during 3AKO and 3CKO infection." (PMID 29709016, 2018). "Deficiency or knockdown of GDF15 in DCs increased the expression of MHCII, CD40,CD80 CD83, and CD86, while over expression of GDF15 either by using GDF15 TG DCs or infection with GDF15-Ad reduced the expression of these molecules, in comparison with WT untreated DCs." (PMID 30425709, 2018). "Interestingly, at the later stages of our infection model, genes essential for correct antigen presentation (CD83, CD40, HLA-DOA) were downregulated exclusively in STM-D23580-infected cells relative to bystander cells." (PMID 30451854, 2018). "Two weeks after initial infection LMP1, 2A and 2B expression will start to contribute to the proliferation of EBV infected B cells via LMP1-dependent NF-κB activation, mimicking CD40 signaling, and LMP2A and 2B’s survival-inducing B cell receptor-like signaling." (PMID 29709016, 2018). "To phenotypically characterise pDC during early P. falciparum infection we assessed maturation markers; CD86, CD40, CD80, HLA-A,B,C, HLA-DR and CD123 (IL-3Rα) expression on pDC before and at peak-infection for participants infected with either 150 pRBC or 1,800 pRBC." (PMID 28572564, 2017). "The percentage of DC, evaluated by CD11c expression, on injection sites and draining lymph nodes is not modify by infection or PSB1115 treatment nor is the expression of CD40 in DC from uninfected mice." (PMID 28791011, 2017). "For the first time, we showed that malaria infection could increase CD40 expression, which in turn enhanced the expression of STING, leading to increased production of IFN-I during early infection and better host survival." (PMID 27716849, 2016). "A large number of studies have been done on CD40; however, the previous studies on CD40 have focused on inflammatory and adaptive immune responses to infection, not stimulation of IFN-I in early innate response." (PMID 27716849, 2016). "The fold changes in luciferase signals in CD40+STING co-transfected cells were much higher than those transfected with CD40 or STING alone, suggesting that CD40 can greatly enhance STING-mediated IFN-I responses to infections." (PMID 27716849, 2016). "Interestingly, these two mutants suggest that EBNA3C has a vital role in CD40 activation, MAP kinase activation and β-Catenin stabilization in B-cells infection and transformation." (PMID 26336822, 2015). "Infected DKO mice succumbed earlier than mice lacking MyD88 alone, while WT and CD40−/− mice survived the infection without signs of severe disease." (PMID 26441965, 2015).
infection (continued). "A significant depletion in the percentage of AMDC was observed at day 4 post-infection that was associated with a change in steady-state CD11b+ and CD11b− AMDC subset frequencies and significantly elevated CD40 and CD80 expression and that returned to baseline by day 14 post-infection." (PMID 25398128, 2014). "There were differences in the expression MHC II, CD40 and CD86 between the naïve APC populations, and changes in expression of these markers suggested that at least a portion of each of the cell populations responded to the infection." (PMID 23390557, 2013). "In the present study, both CD40- and TLR- related pathways were found to be significant, further suggesting a potential interplay between coagulation and host immune response to infection." (PMID 24086587, 2013). "Upon pathogen infection, DCs capture foreign antigen and undergo maturational changes including increased surface expression of major histocompatibility complex (MHC) and costimulatory molecules, such as CD40, CD80, and CD86." (PMID 23301113, 2013). "In the other two APC populations, there was no change in MHC II expression after infection, but there was a significant increase in the percentage of CD40 expressing double positive (CD11c+F4/80+) cells found in infected lungs." (PMID 23390557, 2013). "However, signals from CD40 and high dose TLR ligands can overcome the anergic state of B-1 cells enabling their activation during infection." (PMID 23251136, 2012). "MVA-C infection of human monocyte derived dendritic cells (moDCs) induced the expression of HIV-1 antigens at high levels from 2 to 8 hpi and triggered moDCs maturation as revealed by enhanced expression of HLA-DR, CD86, CD40, HLA-A2, and CD80 molecules." (PMID 22536391, 2012). "This strongly suggests that while CD40 signals are likely involved in the acceleration of T1D by CD11b+CD11c− APCs following CB4 infection, reduction or absence of these signals tips the balance towards Treg induction." (PMID 22355341, 2012). "mRNA expression measured at various time points (1, 3, 12, 24, 36 and 48 hpi) by real-time RT-PCR showed that infection of PK-15 cells with CSFV at either a MOI of 0.1 or 1.0, resulted in down-regulation of seven immune response genes, namely SLA-2, TAP1, SLA-DR, Ii, CD40, CD80, CD86." (PMID 22925563, 2012). "Infection with this pathogen resulted in up regulation of MHC I and MHC II, CD40, CD54, CD58, and CD80, a phenotype consistent with the activation of the DC, suggesting that infected DC produce cytokines that lead to maturation, and possibly to migration and antigen processing and presentation." (PMID 21777464, 2011). "Infection with Tn:Rv0431 resulted in greater expression of transcripts for IL-12p40, IL-6, Delta4, CD40, GM-CSF, RANTES, TNFα and MCP-1, but not GITRL or iNOS, than WT Mtb, both with (not shown) or without IFNγ costimulation." (PMID 21170273, 2010). "Mice lacking CD4 cells (Cd40-/- and class II-/- mice), however, recovered from infection similar to wild type mice." (PMID 20667098, 2010). "For example, while the levels of CD40 and CD80 (data not shown) in MoDCs also increased, it was rather surprising to observe that infection of Mφs with either Bp-844 or Bt-UE5 actually caused a reduction in the levels of CD80 and CD11b." (PMID 19397822, 2009). "The CD40−/− and CD154−/− mice ultimately die ∼4 to 8 weeks post-infection." (PMID 19112490, 2008). "However, in the C. rodentium infection model, despite macrophage infiltration into the lamina propria during the late phase of infection and their likely exposure to CD40 and TLR signaling, these macrophages did not produce IL-23." (PMID 39379604, 2024). "Of note, TRAIL‐R2 was significantly increased post infection also in H29 cells but the increase of LOAd(−) infection in both H29 and T24 was similar to that of LOAd700 or LOAd703 meaning that the increase was not dependent of CD40 stimulation." (PMID 38494863, 2024).